TERT (telomerase reverse transcriptase)
Diseases named in the same sentence as TERT in open-access papers (continued):
Sharing a sentence is not in itself a finding about the gene and the disease.
glioma (continued). "The putative targets of 1p/19q codeletion, tumor suppressor genes FUBP1 and CIC, along with TERT promoter and IDH1/2 variants, generate a unique constellation of genetic aberrations which distinguish these tumors not only from other gliomas, but from most other human cancers." (PMID 31217899, 2019). "The coexistence of BRAF and TERT promoter aberrations characterizes a subset of aggressive glioma." (PMID 31391125, 2019). "The use of ‘omic’ analysis for identification of survival features has had the most success in grade II/III glioma where distinct subtypes of gliomas can be defined by combinations of mutations in isocitrate dehydrogenase (IDH1-R132H), telomerase (TERT) and 1p/19q chromosomal co-deletion." (PMID 31405148, 2019). "However, the level of TERT transcripts varies widely in expression among tumors including gliomas, skin cancers, thyroid cancers, hepatocellular carcinomas, bladder cancers, and malignant lymphomas." (PMID 29693015, 2018). "Furthermore, we confirmed the previously reported associations at 5p15.33 (rs10069690), 9p21.3 (rs634537), 17p13.1 (rs78378222) and 20q13.33 (rs2297440) with TERT-only glioma in each of the three series." (PMID 29460007, 2018). "It would be thus critical to examine the expression level of TERT protein in diffuse gliomas to clarify the role of TERT in their biology in addition to its mRNA level as well as mutational status, but few reports have so far validated the expression of TERT protein in human glioma tissue." (PMID 29693015, 2018). "Moreover, TERT promoter mutations coexist with PIK3CA mutations in 12% of anaplastic thyroid cancers, but only in 7.5% of gliomas." (PMID 29222734, 2018). "Moreover, we substantiate the proposed specific associations between 5p15.33 (rs10069690) and 20q13.33 (rs2297440) variants with TERT promoter mutations, 9p21.3 (rs634537) with TERT-only glioma, as well as 17p13.1 (rs78378222) with TERT-IDH glioma." (PMID 29460007, 2018). "Based on the role of TERT promoter mutations in other tumor entities and the perception that its occurrence is a secondary event in MLS, it is tempting to see clinical similarities between MLS and e.g., gliomas." (PMID 29463038, 2018). "With respect to the 5p15.33 (TERT) and 10q24.33 (OBFC1) loci, it is unclear whether the effect on glioma risk is solely due to telomeres or is pleiotropic and involves multiple factors." (PMID 29460007, 2018). "Unexpectedly, immunohistochemistry using TMab-6 demonstrated that immunoreactivity for TERT did not correspond to the mutational status of the TERT promoter region across glioma samples." (PMID 29693015, 2018). "This is the first extensive analysis on the expression of TERT immunoreactivity in human glioma tissue, suggesting that TERT protein expression may be regulated by several mechanisms in addition to its promoter mutation." (PMID 29693015, 2018). "Future studies with the measurement of TERT activity could be useful for facilitating our understanding of telomere biology in cancer including gliomas." (PMID 29693015, 2018). "TERT immunohistochemistry was not capable of identifying the differences between TERT-mutated gliomas and TERT-nonmutant gliomas." (PMID 29693015, 2018). "This study is the first extensive analysis on the expression of TERT protein in human glioma tissue and suggests that TERT expression could be regulated by various mechanisms including epigenetic modifications." (PMID 29693015, 2018). "Our study is the first thorough analysis on the expression of TERT protein using a specific TERT monoclonal antibody in human glioma tissue, suggesting that TERT protein expression may be regulated by several mechanisms in addition to its promoter mutation." (PMID 29693015, 2018).
glioma (continued). "We found that a novel anti-hTERT mAb TMab-6 specifically recognized human TERT protein, and that it could be applied for immunohistochemistry on the human glioma tissue sections." (PMID 29693015, 2018). "However, TERT transcripts range widely in various cancers including gliomas, and TERT protein expression has been rarely investigated thus far." (PMID 29693015, 2018). "For example, rs10069690 at 5p15.33 is strongly associated with TERT-only glioma, yet the TERT promoter mutation increases telomerase activity without necessarily affecting telomere length." (PMID 29460007, 2018). "Although the practical diagnostic utility of the antibody to detect the TERT-mutated tumors was expected, TERT immunohistochemistry was not capable of identifying the differences between TERT-mutated gliomas and TERT-nonmutant gliomas." (PMID 29693015, 2018). "In addition to the integrated phenotypic and genotypic features of glioma, many genetic studies have found that common inherited variants near several genes (TERC, TERT, EGFR, CDKN2B, PHLDB1 and RTEL1) are associated with increased risk of adult glioma." (PMID 30462709, 2018). "Next, Prof. Yu Yao from Huashan Hospital of Fudan University reported the recent progress of his team in glioma immunology after stating the importance of genes encoding IDH1 and telomerase reverse transcriptase (TERT), as well as 1p/19q codeletion in classifying glioma." (PMID 28797870, 2017). "In addition to IDH and 1p/19q status, two mutations in the promoter region of the telomerase reverse transcriptase (TERT) gene are frequently identified in various types of cancer, including glioma." (PMID 28915660, 2017). "TERT mutation glioma apparently present with non-midline distribution while sitting in right frontal-insular lobe and left basal ganglia region." (PMID 28915860, 2017). "Moreover, TERT is utilized for molecular sub-classification of gliomas and is a prognostic and predictive molecular marker of glioma." (PMID 29262650, 2017). "In particular, TERT and ATRX mutations are mutually exclusive in gliomas, suggesting either mutation in one of the major genes associated with TA or ALT as TMM may be sufficient to avoid replicative senescence by telomere loss and to drive glioma formation." (PMID 28513547, 2017). "In addition, we also investigated the relationship between TERT promoter mutations and the RTL in gliomas." (PMID 26556853, 2016). "Similarly, other comprehensive studies suggest that the combined analysis of the mutational status of TERT, IDH, and 1p/19q deletion had the ability to define the biological and clinical behavior of gliomas better than analysis based solely in histology." (PMID 27172220, 2016). "More recently, a large cohort study described five glioma groups based on 1p/19q codeletion, IDH1/2 and TERT promoter mutational profile, with important clinical impact, with the “triple-negative” group or the only TERT-mutated group exhibiting a higher mortality risk." (PMID 27172220, 2016). "TERT promoter mutations (HR = 1.49, 95% CI, 1.05–2.10; P = 0.026) and long RTL (HR = 1.50, 95% CI, 1.04–2.17; P = 0.030) were significantly associated with poor survival in glioma patients." (PMID 26556853, 2016). "In addition, coexisting TERT promoter mutations and long RTL were also found in 55 of 330 (16.7%) gliomas." (PMID 26556853, 2016). "There was a significantly positive relationship between TERT promoter mutations and ATRX activation (Χ2 = 27.289, P < 0.001) in gliomas, as supported by the previous studies that TERT promoter and ATRX mutations (usually caused ATRX inactivation) were mutually exclusive." (PMID 26556853, 2016). "Among them, TERT promoter (TERTp) mutations C228T and C250T were recently described in gliomas and a possible relation with rs55705857 has never been explored so far10." (PMID 27282637, 2016).
glioma (continued). "Increasing evidences have implicated somatic gain-of-function mutations at the telomerase reverse transcriptase (TERT) promoter as one of the major mechanisms that promote transcriptional activation of TERT and subsequently maintain telomere length in human cancers including glioma." (PMID 26556853, 2016). "As expected, TERT promoter mutations were closely associated with WHO grade, suggesting that these mutations may contribute to clinical outcomes of glioma patients." (PMID 26556853, 2016). "As expected, we found highly frequent ATRX inactivation (∼92.9%) in TERT wild-type gliomas in the present study, and demonstrated that the RTL was significantly longer in ATRX-negative tumors than that in ATRX-positive tumors (Median, 0.90 vs. 0.49; P = 0.002)." (PMID 26556853, 2016). "Another clinical report showed that −124C>T or −146C>T mutations were associated with poor OS in grade IV gliomas, but the effect was confined to the patients who did not carry the variant G-allele for the rs2853669 polymorphism at the TERT promoter." (PMID 27438857, 2016). "Similarly, decreased GS(P) level and increased glycogen accumulation observed upon siRNA-mediated knock-down of TERT indicated that glycogen metabolism in glioma cells is hTERT regulated." (PMID 27148686, 2016). "In addition, a very recent study reveals that the transcription factor GABP selectively binds and activates the mutant TERT promoter, also contributing to aberrant expression of TERT gene in multiple cancers, including gliomas." (PMID 26556853, 2016). "In lower grade gliomas with IDH mutations and 1p19q co-deletion, the authors found frequent mutations in CIC, FUBP1, PI3 kinase pathway genes, NOTCH1, ZBTB20, and ARIDIA, in addition to activating TERT promoter mutations." (PMID 26244119, 2015). "Results from measurement of relative telomere length were available for 285 gliomas of which 190 were with and 95 were without TERT promoter mutations." (PMID 25797251, 2015). "Among patients with Grade II and III gliomas, survival was best in the IDH and TERT mutation group." (PMID 26485760, 2015). "Furthermore, we and others showed that TERT promoter mutations in combination with IDH mutation, are promising prognostic indicators of survival in glioma." (PMID 26314843, 2015). "Gliomas with TERT mutations in the presence of 1p/19q codeletion (i.e., oligodendrogliomas), have a very favorable outcome where the same TERT mutations in the absence of this codeletion or IDH mutations herald a grim prognosis (comparable to glioblastoma)." (PMID 25943885, 2015). "Because the association between glioma risk and LTL remained significant even after excluding the TERC, TERT and RTEL1 SNPs from the LTL calculations, it is unlikely that the association observed in our data could be entirely attributable to pleiotropy." (PMID 26646793, 2015). "As such, TERT mRNA expression level has been suggested as a biomarker for gliomas." (PMID 24937153, 2014). "A luciferase reporter assay was used to test whether transcriptional activity from the mutated TERT promoter changed as a result of hypoxia and TMZ treatment in the U87 glioma cell line." (PMID 24937153, 2014). "This study explored the effects of telomerase reverse transcriptase (TERT) promoter mutations on transcriptional activity of the TERT gene under hypoxic and temozolomide (TMZ) treatment conditions, and investigated the status and prognostic value of these mutations in gliomas." (PMID 24937153, 2014).
glioma (continued). "The sustained upregulation of TERT expression implies a continuous activation of telomerase, which could contribute to the immortalization of glioma cells and their resistance to therapeutic measures." (PMID 24937153, 2014). "Given the background genes previously discovered in glioma, we hypothesize TERT promoter and IDH1/2 mutations as the major driver genes that are consistently found in low-grade and high-grade adult gliomas." (PMID 24722048, 2014). "TERT mRNA expression in gliomas was examined by real-time PCR." (PMID 24937153, 2014). "Among 152 tumor samples, TERT promoter mutations were found only in gliomas, and not in meningiomas, pituitary adenomas, cavernomas, intracranial metastases, normal brain tissues, or in peripheral blood samples." (PMID 24937153, 2014). "TERT promoter mutations maintained its ability of inducing high transcriptional activity even under hypoxic and TMZ treatment conditions, and the presence of mutations was associated with poor prognosis in glioma patients." (PMID 24937153, 2014). "Tumors that did not harbor mutations in either the TERT promoter or IDH1/2 comprised a unique clinical group with a short OS (median OS 17.2 months) that was distinct from TERT promoter mutated gliomas (median OS 11.5 months)." (PMID 24722048, 2014). "TERT expression also correlates with glioma grade and prognosis." (PMID 22221621, 2012). "However, one previous study showed that histological grade was still an important prognostic factor for IDH-wildtype gliomas and suggested to be cautious when classifying IDH-wildtype grade II astrocytomas as glioblastomas, especially those with isolated TERT promoter mutation." (PMID 41035663, 2025). "As for pediatric‐type gliomas, our study did not identify any TERT promoter mutations." (PMID 39804195, 2025). "Moreover, TERT mutation has been associated with resistance to anti-growth factors and increased angiogenesis, which pair with the higher DSC-rCBV and DCE-ve in TERT promoter mutant IDH-wild-type gliomas." (PMID 40870498, 2025). "Moreover, to the best of our knowledge, no previous studies have explored TERT promoter mutations specifically in the newly defined pediatric‐type glioma subgroup." (PMID 39804195, 2025). "However, in 2021, the WHO introduced updated classification criteria for gliomas, and IDH wild-type astrocytomas with EGFR amplification, chromosome 7 acquisition with chromosome 10 deletion and TERT promoter mutations are also included in glioblastoma if they have any of the molecular phenotypes." (PMID 39944539, 2025). "After selecting factors in penalized cox models, patient age, deep tumor location, WHO grade 4, marked enhancement intensity, IDH (mutation/wild type), and TERT promoter mutation status (positive/negative) were identified as independent risk factors for OS in the unifocal glioma group." (PMID 40496616, 2025). "Testing IDH wild type gliomas if bearing EGFR amplification, TERT promoter region mutation, or chromosome 7 gain and chromosome 10 loss genetic alterations versus other gliomas, could be similarly used to classify glioblastoma (WHO classification 5th edition 2021) samples." (PMID 39578301, 2025). "Moreover, NGS of glioma is now justified to look for CDKN2A/B homozygous deletions that upgrade IDH-mutant astrocytomas to grade IV, and EGFR amplification, chromosome (+ 7/-10) and TERT promoter mutations that upgrade IDHwt astrocytomas to grade IV." (PMID 39361075, 2024). "Moreover, despite the absence of histological features of high‐grade malignancy (necrosis, angiogenesis), an IDHwt glioma can still be classified as GBM when EGFR amplification, the combination of gain of chromosome 7 and loss of chromosome 10 (7+/10‐), and TERT promoter mutation are present." (PMID 36776000, 2023). "Therefore, identifying IDH‐mutant TERT promoter‐mutant (IDH‐mut TERTp‐mut) gliomas may help prognosis prediction and treatment selection." (PMID 36176070, 2023).
glioma (continued). "According to data analysis results, in four genetic models (AM, RM, DM and C-DM) TERT gene rs2736100 polymorphism, CCDC26 gene rs4295627 polymorphism, CDKN2A/B gene rs4977756 polymorphism and RTEL1 gene rs6010620 polymorphisms increased the risk of glioma in Caucasians to different degrees." (PMID 37746290, 2023). "It is compatible with Illumina Novaseq 6000 (JAX SOMASEQ - Clinical test - NIH Genetic Testing Registry GTR - NCBI, 2023) and could be used for the diagnosis of glioma, however, it misses p-TERT DNA sequence alterations, p-MGMT methylation, and important CNVs such as 1p/19q codeletion." (PMID 37908227, 2023). "The 5p15.33 region encompassing the TERT-CLPTM1L genes has been associated with the risks of at least 11 different cancers, including lung, prostate, breast, pancreatic, bladder, esophageal, endometrial, gastric, and head and neck cancers, glioma, and melanoma." (PMID 36769103, 2023). "Kaplan-Meier survival curve showed that IDH1/2 gene and TERT promoter mutation were significantly different from those of wild-type patients, again, it is suggested that IDH1/2 gene and TERT promoter mutations are related to the survival of patients with glioma." (PMID 37250582, 2023). "Second, we could not classify the IDH-wt glioma further due to the missing molecular information (such as the TERT promoter mutation and EGFR amplification)." (PMID 35741587, 2022). "In recent years, various molecular markers have been discovered for gliomas, including isocitrate dehydrogenase 1 and 2 (IDH 1/2) mutations, codeletion of chromosome arms 1p and 19q (1p19q co-del) and telomerase reverse transcriptase promoter (TERT-p) hotspot mutations." (PMID 35495630, 2022). "Therefore, this study aimed to firstly investigate the association between WHO grade and the ADC values of gliomas, secondly evaluate the predictive capability of ADC in genetic markers (e.g., IDH, MGMT, and TERT) in gliomas, thirdly confirm the parameters that affect the ADC values." (PMID 36471242, 2022). "Recent studies showed that the GABP tetramer forming isoforms, especially GABPB1-L, activate the mutant TERT promoter and a disruption of B1L generates telomeric loss in glioblastoma cell lines introducing the importance of GABPA/B isoforms in the mutated TERT promoter dependent gliomas." (PMID 34194624, 2021). "However, CHI3L2 expression levels of glioma cells were not significantly related to gender, location, TERT promoter mutation status, and MGMT promoter methylated status." (PMID 33937022, 2021). "Moreover, the transcription of TERT in a cohort of low grade gliomas and sec." (PMID 34194624, 2021). "Our studies with NHAs that were engineered to express TERT or to be ATRX-deficient in the absence of IDHmut suggest these 1H-MRS-detectable biomarkers are observed in the context of IDHmut-expressing low-grade gliomas." (PMID 33397920, 2021). "Importantly, we have leveraged this information to mechanistically validate hyperpolarized [1-13C]-alanine flux to pyruvate as an imaging biomarker of ALT status and hyperpolarized [1-13C]-alanine flux to lactate as an imaging biomarker of TERT status in low-grade gliomas." (PMID 33397920, 2021). "We therefore can propose that GABP might be a potential biomarker in glioma classification, but further investigations must be made in order to elucidate the actual relationship between TERT and GABPA/B isoforms in gliomas, aiming for targeted therapy in the future." (PMID 34194624, 2021). "In summary, TERT promoter mutation should not be used as a single predictive factor in gliomas." (PMID 32957941, 2020). "Interestingly, high TERT activity occurs in 90% of human cancers, including gliomas (70%)." (PMID 32957941, 2020). "In contrast to TERT promoter mutation, the prognostic impact of MGMT methylation was not dependent on other confounding factors including the status of TERT promoter mutation, emphasizing the important role of MGMT methylation as an independent prognostic marker in gliomas." (PMID 32957941, 2020).